CXCL8 (C-X-C motif chemokine ligand 8)
Description:
Chemotactic factor that mediates inflammatory response by attracting neutrophils, basophils, and T-cells to clear pathogens and protect the host from infection. Also plays an important role in neutrophil activation. Released in response to an inflammatory stimulus, exerts its effect by binding to the G protein-coupled receptors CXCR1 and CXCR2, primarily found in neutrophils, monocytes and endothelial cells. G protein heterotrimer (alpha, beta, gamma subunits) constitutively binds to CXCR1/CXCR2 receptor and activation by IL8 leads to beta and gamma subunits release from Galpha (GNAI2 in neutrophils) and activation of several downstream signaling pathways including PI3K and MAPK pathways.
Synonyms: IL-8; GCP-1; MDNCF; MONAP; NAP-1; LYNAP; NAF; IL8; SCYB8; LUCT; LECT; TSG-1; 3-10C; AMCF-I; b-ENAP; K60; GCP1; NAP1
Tractability: Small molecule: a structure with a bound ligand is known; a high-quality ligand is known; it has a binding pocket of medium quality; it belongs to a druggable protein family. Antibody: a drug acting on it is in phase 2 or 3 trials; its Gene Ontology location is reachable by antibodies, with high confidence; UniProt places it where antibodies can reach, with medium confidence; UniProt predicts a signal peptide or a membrane-spanning region. PROTAC: a small molecule that binds it is known.
Target class: Secreted protein
Safety:
Unwanted effects reported when the protein is acted on. In parentheses: how it was acted on, where the effect was seen, and who reports it.
hypertension (source: ClinPGx)
Gene: Protein-coding gene on chromosome 4 (73,740,519 to 73,747,379, forward strand). Ensembl gene ENSG00000169429.
Subcellular location: Secreted
Subcellular location (Human Protein Atlas): Golgi apparatus; Predicted to be secreted
Pathways (Reactome):
Signal Transduction: Chemokine receptors bind chemokines; G alpha (i) signalling events; Peptide ligand-binding receptors
Cellular responses to stimuli: ATF4 activates genes in response to endoplasmic reticulum stress; Senescence-Associated Secretory Phenotype (SASP)
Immune System: Interleukin-10 signaling; Interleukin-4 and Interleukin-13 signaling
Gene Ontology:
Molecular function: chemokine activity; CXCR chemokine receptor binding; cytokine activity; heparin binding; interleukin-8 receptor binding; protein binding
Biological process: cellular response to fibroblast growth factor stimulus; cellular response to interleukin-1; cellular response to lipopolysaccharide; cellular response to tumor necrosis factor; embryonic digestive tract development; induction of positive chemotaxis; interleukin-8-mediated signaling pathway; intracellular signal transduction; negative regulation of cell adhesion molecule production; negative regulation of G protein-coupled receptor signaling pathway; negative regulation of gene expression; neutrophil activation; neutrophil chemotaxis; positive regulation of angiogenesis; positive regulation of gene expression; receptor internalization; regulation of cell adhesion; regulation of entry of bacterium into host cell; regulation of single stranded viral RNA replication via double stranded DNA intermediate; response to endoplasmic reticulum stress; response to molecule of bacterial origin; angiogenesis; antimicrobial humoral immune response mediated by antimicrobial peptide; calcium-mediated signaling; chemotaxis; and 11 more
Cellular component: extracellular region; G protein-coupled receptor complex; membrane
Genetic constraint (gnomAD): Loss-of-function variants: 6 observed, 5.62 expected, observed/expected ratio (o/e) 1.07, 90% interval 0.57 to 1.82. That is too few expected variants to judge how well the gene tolerates losing a copy. Missense variants: 101 observed, 81 expected, observed/expected ratio (o/e) 1.25, 90% interval 1.06 to 1.47. Synonymous variants: 28 observed, 28.61 expected, observed/expected ratio (o/e) 0.98, 90% interval 0.72 to 1.34.
Homologues: Orthologues: chimpanzee CXCL8 (100% identical), macaque CXCL8 (95% identical), rabbit CXCL8 (80% identical), dog CXCL8 (76% identical), pig CXCL8 (76% identical), guinea pig CXCL8 (70% identical), tropical clawed frog cxcl2 (39% identical). Paralogues in human: CXCL1 (41% identical), CXCL2 (41% identical), CXCL3 (40% identical), PPBP (39% identical), CXCL5 (31% identical), CXCL13 (30% identical), CXCL6 (28% identical), CXCL9 (28% identical), PF4 (27% identical), PF4V1 (27% identical), CXCL10 (25% identical), CXCL11 (22% identical).
Diseases named in the same sentence as CXCL8 in open-access papers:
CXCL8 is named in the same sentence as 1,378 diseases in open-access papers, as found by Europe PMC text mining. Sharing a sentence is not in itself a finding about the gene and the disease. The quoted sentences say what the papers report.
COVID-19 (1,048 papers, 2020 to 2026). A disease caused by infection with severe acute respiratory syndrome coronavirus 2. "Six genes, including TNF, CXCL8, IL-6, IL-1β, IL-2, and IL-10, were associated with three major signaling pathways: the COVID-19 adverse outcome pathway, an overview of pro-inflammatory and pro-fibrotic mediators, and the interleukin-10 signaling pathway." (PMID 40166075, 2025). "Elevated levels of plasma CXCL8 have been associated with increased mortality in patients with COVID-19." (PMID 40371107, 2025). "In contrast, inflammatory mediators associated with severe COVID-19 including CXCL-8, TREM-1 are increased with age." (PMID 38515147, 2024). "When COVID-19 progresses to severe illness, higher serum levels of IL-6, CXCL8, TNF-α, and IL-1β are associated with hyperinflammatory and hyper-coagulable conditions." (PMID 37908356, 2023). "Severe cases of COVID-19 are associated with prolonged, heightened levels of cytokines, such as IL-6, IL-8/CXCL8, CXCL9, CXCL10, TNF-α, MCP1/CCL2, RANTES/CCL5, IL-18, and MIP-1α/CCL3, which can last for up to two months." (PMID 36983995, 2023). "Infections associated with COVID-19, however, have been associated with high serum levels of IL-6, CXCL8, and CXCL10." (PMID 37109156, 2023). "Conversely, the Severe-Death group was marked by a strong positive correlation between CXCL8, D-dimer and monocytes, factors associated with COVID-19 severity among the general population, and in solid tumor patients specifically." (PMID 36700209, 2022). "Moderate and severe COVID-19 caused by all variants cause an increase in CXCL8/IL-8 levels in the blood." (PMID 36613652, 2022). "Although LPS stimulation represents an experimental model of bacterial infection, this result is important, since IL-8 (CXCL-8) is a chemoattractant cytokine that specifically targets neutrophils, which are inflammatory cells implicated in COVID-19 severity." (PMID 34641348, 2021). "Of the proinflammatory cytokines, the following are of particular interest: CCL20, which has been associated with the first severe acute respiratory syndrome coronavirus (SARS-CoV), and IL-1B, CXCL1, CXCL2, and CXCL8, which are associated with COVID-19." (PMID 32752138, 2020). "CCL2, CXCL10, and CXCL8 are the most commonly found chemokines associated with COVID-19 severity." (PMID 35782361, 2022). "Monocyte-derived macrophages have also been linked as a possible source of pro-inflammatory cytokines, TNF, CXCL-8, IL-1, and IL-8 during severe COVID-19, therefore suggesting a strong association between monocyte-derived macrophages and COVID-19 disease severity." (PMID 36072602, 2022). "Therefore, we linked comparably elevated IL1B and CXCL8 values to the emerging role of neutrophil activation in both KD and severe COVID-19." (PMID 36159873, 2022). "Although the exact pathway of COVID-19 pathogenesis is still unknown, recent data have demonstrated that elevated levels of pro-inflammatory cytokines in serum, including CXCL8, are associated with enhanced disease pathogenesis and mortality." (PMID 35632741, 2022). "The production of CXCL8, a known neutrophil chemoattractant, is consistent with reports describing a high number of circulating neutrophils and associated injury in the airway and lung tissues of COVID-19 patients." (PMID 35632741, 2022). "IL-8, encoded by the CXCL8 gene, was proposed to be a better biomarker of the COVID-19 outcome than IL-6, as IL-6 may activate the pro- and anti-inflammatory pathways." (PMID 34571838, 2021). "However, it should be noted that PF-4, LF, IL-8 (CXCL8), and polyarginine neutralize the anticoagulant activity of heparin, particularly in COVID-19 patients associated with thrombocytopenia and LF and IL-8 upregulation." (PMID 33954061, 2021). "High levels of IL6 and CXCL8 are associated with severe cases of COVID-19 pathogenesis." (PMID 33362771, 2020). "It has been observed that when CXCL8 expression is higher, IL-8 also increases, which correlates with COVID-19 disease severity." (PMID 41301889, 2025).
COVID-19 (continued). "A small proportion of moDCs also expressed CXCL8 and showed reduced enrichment of antigen presentation genes in acute COVID-19, in contrast to NALT cDCs." (PMID 39890933, 2025). "The GS ‘Coronavirus disease—COVID-19’ included several downregulated genes involved in innate immunity and inflammation, such as C-X-C motif chemokine ligand 8 (CXCL8) and toll like receptor 2 (TLR2)." (PMID 40559872, 2025). "Elevated CXCL8 levels have also been reported in early COVID-19 patients’ blood and alveolar spaces, with higher levels in severe cases but no significant increase in mild cases compared to healthy controls." (PMID 41155463, 2025). "Key biomarkers of COVID-19, such as CXCL8, S100A9, and HLA class I genes, have been identified as critical hub genes and the main players within these networks." (PMID 40580453, 2025). "The consistent upregulation of CXCL8 across the SARS-CoV-2 ancestral strain and variants, along with elevated IL-8 release from MKs exposed to SARS-CoV-2 variants and in COVID-19 patient plasma, underscores its potential as a biomarker for disease severity." (PMID 40702756, 2025). "Conversely, species such as Bacteroides dorei and Akkermansia muciniphila, which were enriched in the COVID-19 cohort, positively correlated with proinflammatory cytokines IL-1β, IL-6, and CXCL8, potentially exacerbating inflammation." (PMID 39518964, 2024). "CXCL-8 attracts neutrophils to the site of inflammation and was found to be elevated in both mild and patients with severe COVID-19 and increased with disease progression." (PMID 38515147, 2024). "Interactions between the five genes shared by all the investigated metals and COVID-19 (CXCL8, IL1B, IL10, IL6, and TNF) are mainly physical, whereas the dominant interaction between the genes affected by individual metals is co-expression." (PMID 38963144, 2024). "CXCL8 elevation is a prognostic marker for those at a high risk of ARDS and of patients at a high risk of experiencing severe COVID-19." (PMID 38991709, 2024). "Within these, inflammatory markers previously associated with COVID-19 severity were among the high-contribution features of the severity factor, including IL6, CXCL10, and CXCL8 (IL8) proteins in serum." (PMID 38690733, 2024). "A significant change in cytokine (including IFN-α, β, and γ; IL-2, IL-6, IL-7, IL-12, and IL-1β) and chemokine (including CCL 2, 3, and 5; CXCL10, CXCL9, and CXCL8) levels in severe COVID-19 cases was also found." (PMID 38255322, 2024). "The main inflammatory cytokines and chemokines widely produced by patients with severe forms of COVID-19 are IL-6, IL-8, IL-1β, TNF-alpha, IFN-gamma, MIP1α and 1β, CCL2, CCL5, CCL20, CXCL1, CXCL2, CXCL8, CXCL10, and CXCL17." (PMID 39768136, 2024). "The increased presence of chemokines CCL2, CCL4, CXCL8, and CXCL10 in the plasma was observed among the Wuhan, Alpha, Delta, and Omicron variants of moderate to severe COVID-19 patients when compared to healthy individuals." (PMID 37632046, 2023). "Megakaryocytes can also contribute to inflammatory signaling however no upregulation of inflammatory-related genes (e.g., CCL2, CLL3, IL-6 and CXCL8, etc.)were observed in the megakaryocytes from COVID-19 patients including those with encephalopathy." (PMID 37848421, 2023). "Heatmap showed upregulation of genes (e.g., TMPRSS2, JUN and CXCL8) related to the COVID-19 signalling pathway upon DCM treatment at a concentration of 200 μM, compared with concentrations of 0 μM and 100 μM." (PMID 37301869, 2023). "In agreement, hyperactivated neutrophils in the BAL fluid of COVID-19 patients were characterized by higher expression of CXCL8 and they seem to play a critical role in COVID-19 pneumonia." (PMID 37104043, 2023). "We and others found elevated levels of CXCL8, neutrophils, and neutrophil degranulation products in the blood of hospitalized COVID-19 patients compared to healthy controls." (PMID 36725964, 2023).
COVID-19 (continued). "Vector analysis conducted in the 1st trimester indicated that CXCL8, CCL3, CCL5, IL-1β, TNF-α, IL-12, IL-15, IL-1Ra, IL-10, and G-CSF were associated with convalescent COVID-19 in pregnant women." (PMID 37122732, 2023). "A few genes, as NFKBIA, ICAM1, CXCL8, and TNFAIP3 are involved in NF-κB signaling and TNF signaling pathways, which have been known to cause inflammation and cytokine storms, augmenting COVID-19 severity." (PMID 37701571, 2023). "Within BAL fluids, highly increased levels of CXCL8 and other neutrophil attractants were detected in COVID-19 patients in the intensive care unit (ICU) compared to influenza ICU patients." (PMID 36725964, 2023). "Another study has confirmed these data showing that serum levels of several pro-inflammatory mediators such as IL-6, CXCL8 and TNFα and also serum NETs levels are increased in COVID-19 patients (n = 27), compared to healthy subjects (n = 12)." (PMID 36941580, 2023). "Measurement of plasma CXCL8 replicated previously reported data, showing elevated CXCL8 in COVID-19 patients compared with healthy controls, with a trend for increased levels in severe patients." (PMID 36622345, 2023). "Given that neutrophilia is frequently observed in patients with COVID-19, it is possible that CXCL8 contributes to the pathophysiology of the disease." (PMID 35303909, 2022). "In severe COVID-19 patients, systemic and neutrophil autocrine CXCL8 positive feedback loops initiate neutrophil activation, degranulation and NET formation, which exacerbate neutrophil-driven immunopathology." (PMID 36532016, 2022). "Regarding the chemokines, COVID-19 patients showed gene expression levels of CXCL8 and CXCL9 similar to control subjects, but increased expression levels of CXCL10 and CXCL11 (by 290% and 150%, respectively)." (PMID 36009555, 2022). "We observed increased levels of chemokines MCP-1 (CCL2), IP-10 (CXCL10), MIP1β (CCL4) and IL-8 (CXCL8) in COVID-19 patients." (PMID 35529862, 2022). "It was previously reported that CXCL8 mRNA is significantly upregulated following infection of cells with SARS-CoV-2 and that the levels of IL8 are increased in COVID-19 patients." (PMID 35293857, 2022). "Considering the discovery of CXCL8 as an IL-1β–induced protein, we found that COVID-19 BAL fluid levels of CXCL8 and IL-1β correlated positively with each other and with levels of IL-17A." (PMID 34793331, 2022). "We observed a reduction of CCL-2/MCP-1 and CXCL8/IL-8 peripheral levels after 12 weeks of supervised exercise in patients post-COVID-19." (PMID 36685603, 2022). "In fatal COVID-19 cases, the chemokines CXCL8, CCL2, and CCL3were significantly elevated, but they were increased similarly in mild and severe cases during the early stages of infection and remained at steady levels afterwards in the mild cases." (PMID 36016187, 2022). "Mon HLA and Mon CD14 inside Delta samples differ in expression for the cytokine panel (CCL3, VEGFA, CCL5, CCL4, CXCR4, IL7R, CXCL8, and PF4) that have been found associated with COVID-19 severity and mortality." (PMID 36230912, 2022). "Among the enriched significant pathways, the Coronavirus disease-COVID-19-related pathways is the most significant pathway which involved most of the hHub-DEGs notably, CXCL8, EGFR, IL6, JUN, MAPK1, STAT3, TNF, and UBA52." (PMID 36016137, 2022). "In this regard, it has been discussed that high production of some chemokines, such as CXCL8/IL-8, CCL-2/MCP-1, CCL3, CCL5, CXCL9, and CXCL10 are associated with lung damage and COVID-19 severity." (PMID 36685603, 2022). "In COVID-19, CXCL8 expression was higher only in severe patients, and positively correlated with the percentage of neutrophils, which proposed that CXCL8 leads to deterioration of the condition by recruiting neutrophils." (PMID 35037831, 2022). "In COVID-19, confirmed greater expression of pro-inflammatory cytokines and chemokines along with CXCL8." (PMID 36016187, 2022).